ZNF112 (zinc finger protein 112)
Description:
May be involved in transcriptional regulation.
Synonyms: ZFP112; ZNF228
Tractability: PROTAC: UniProt records ubiquitination sites on it; ubiquitination databases record sites on it.
Gene: Protein-coding gene on chromosome 19 (44,326,555 to 44,367,217, reverse strand). Ensembl gene ENSG00000062370.
Subcellular location: Nucleus
Subcellular location (Human Protein Atlas): Nucleoplasm; Nucleoli fibrillar center
Pathways (Reactome):
Gene expression (Transcription): Generic Transcription Pathway
Gene Ontology:
Molecular function: transcription cis-regulatory region binding
Biological process: regulation of transcription by RNA polymerase II; regulation of DNA-templated transcription
Cellular component: fibrillar center; nucleoplasm; nucleus
Genetic constraint (gnomAD): Loss-of-function variants: 35 observed, 78.88 expected, observed/expected ratio (o/e) 0.44, 90% interval 0.34 to 0.59. The upper end of that interval is the gene's LOEUF score, 0.59, which puts it in group 2 of 6, group 1 being the genes least tolerant of losing a copy. Missense variants: 927 observed, 1,104.8 expected, observed/expected ratio (o/e) 0.84, 90% interval 0.79 to 0.89. Synonymous variants: 321 observed, 371.47 expected, observed/expected ratio (o/e) 0.86, 90% interval 0.79 to 0.95.
Homologues: Orthologues: chimpanzee ZNF112 (98% identical), macaque ZNF112 (96% identical), dog ZNF112 (83% identical), pig ZNF112 (69% identical), guinea pig ZNF112 (67% identical), rat Zfp112 (63% identical), mouse Zfp112 (62% identical), rabbit ZNF112 (57% identical). Paralogues in human: ZNF226 (40% identical), ZNF229 (39% identical), ZNF234 (37% identical), ZNF235 (35% identical), ZNF45 (34% identical), ZNF227 (34% identical), ZNF658 (32% identical), ZNF841 (32% identical), ZNF28 (31% identical), ZNF836 (31% identical), ZNF33B (31% identical), ZNF254 (30% identical), and 164 more.
Diseases named in the same sentence as ZNF112 in open-access papers:
ZNF112 is named in the same sentence as 3 diseases in open-access papers, as found by Europe PMC text mining. Sharing a sentence is not in itself a finding about the gene and the disease. The quoted sentences say what the papers report.
leukemia (2 papers, 2021 to 2024). A malignant (clonal) hematologic disorder, involving hematopoietic stem cells and characterized by the presence of primitive or atypical myeloid or lymphoid cells in the bone marrow and the blood. "BCRF8C and ZNF112 engrafted mice succumbed from leukemia after approximately 22 and 28 days, respectively, with relative lower levels of GFP + leukemia cells in the PB compared to ∼ 15 days for BBC2 cells." (PMID 38730491, 2024). "To determine whether IRAK1 has a broader influence on different leukemia subtypes, we used CRISPR/Cas9 to knock out IRAK1 in ZMYM2-FGFR1 expressing ZNF112 cells, which predominantly show a T-cell ALL immunophenotype." (PMID 34906138, 2021).
Kawasaki disease (1 paper, 2023). A rare inflammatory disease characterized by an acute febrile, systemic, self-limiting, medium-vessel vasculitis primarily affecting children. "ZNF112 gene, on the other hand, has been linked to immunoglobulin resistance in Kawasaki Disease (KD) possibly due to its regulatory contribution to inflammation." (PMID 37664632, 2023).
T-cell leukemia (1 paper, 2024). A malignant disease of the T-lymphocytes in the bone marrow, thymus, and/or blood. "To extend these studies to other SCLL models, we performed the same flow cytometric analysis in mice engrafted with the AML-like BCRF8C cells expressing BCR-FGFR1 and ZNF112 T-cell leukemia cells expressing the ZMYM2-FGFR1 chimeric kinase." (PMID 38730491, 2024).